HLA-E (major histocompatibility complex, class I, E)
Diseases named in the same sentence as HLA-E in open-access papers (continued):
Sharing a sentence is not in itself a finding about the gene and the disease.
ovarian carcinoma (16 papers, 2016 to 2025). A malignant neoplasm originating from the surface ovarian epithelium. "HLA-G and HLA-E in ovarian cancer are potentially associated with the mechanism of disease progression." (PMID 34868310, 2021). "HLA-E*0103 has been associated with higher susceptibility to cancer diseases such as acute leukemia and ovarian cancer, as well as with an increased risk of mortality in patients with chronic lymphocytic leukemia." (PMID 33375572, 2020). "Our previous study also indicated that HLA-E protein was overexpressed in ovarian cancer tissues compared with normal ovary tissues." (PMID 38007483, 2023). "In the present study, we found a positive correlation between IFN-γ and HLA-E expression in ovarian cancer tissues." (PMID 38007483, 2023). "IFN-γ then upregulates HLA-E expression in ovarian cancer cells, which presents peptides to inhibitory receptors on NK cells." (PMID 38007483, 2023). "The mechanism to induce HLA-E overexpression by IFN-γ was explored using human ovarian cancer cell lines through western blot and flow cytometry." (PMID 38007483, 2023). "The percentage of HLA-E or IFN-γ positive cells in ovarian cancer tissues was significantly higher than in controls." (PMID 38007483, 2023). "We found that HLA-E mRNA and protein expression was significantly upregulated in two ovarian cancer cell lines." (PMID 38007483, 2023). "HLA-E is significantly upregulated in ovarian cancer tissues, and HLA-E presents peptides to inhibitory receptor CD94/NKG2A or stimulatory receptor CD94/NKG2C expressing on the majority of NK cells." (PMID 38007483, 2023). "HLA-E appears to be a robust prognostic biomarker and preferentially overexpressed in homologous recombination deficiency (HRD) ovarian cancers." (PMID 35267497, 2022). "We identified a strong link between HRD and HLA-E expression that brings a promising strategy through CD94/NKG2A targeting in HRD positive ovarian cancer." (PMID 35267497, 2022). "Although classical HLA alleles are frequently lost in human cancer to prevent T-cell recognition, the upregulation of HLA-E is a common feature in several cancer entities including ovarian cancer." (PMID 35267497, 2022). "The better survival rate of ovarian cancer patients with infiltrating CD8+ T cells disappears when NKG2A signaling is activated by high HLA-E expression." (PMID 28623356, 2017). "We have studied the expression of HLA-E in different cancers and found that the beneficial prognostic effect of infiltrating CTLs in ovarian cancer was thwarted by high expression of HLA-E." (PMID 26658106, 2016). "In this paper, the expression of IFN-γ and HLA-E was detected in ovarian cancer tissues." (PMID 38007483, 2023). "The mechanism of IFN-γ-induced HLA-E upregulation was investigated using ovarian cancer cell lines." (PMID 38007483, 2023). "The differential expression of HLA-E protein between ovarian cancer and normal tissues may be controlled by post-transcriptional regulation." (PMID 38007483, 2023). "Indeed, HLA-E on freshly isolated ovarian cancer cells was up-regulated by IFN-γ treatment, while the role of type I IFN in the regulation of HLA-E expression is still an open question." (PMID 35267497, 2022). "IFN-γ-induced overexpression of HLA-E could protect ovarian cancer cells from NK lysis." (PMID 38007483, 2023). "HLA-E and IFN-γ expression in tissue microarray with 20 normal ovary tissues and 20 ovarian cancer tissues was detected by multiplexed immunohistochemistry." (PMID 38007483, 2023). "The expression of leukocyte antigen-E (HLA-E), IFN-γ, CD3 and CD56 in clinical samples of ovarian cancer was detected by mutiplexed immunohistochemistry." (PMID 38007483, 2023). "There was a positive correlation between HLA-E and IFN-γ expression in ovarian cancer tissues." (PMID 38007483, 2023).
ovarian carcinoma (continued). "MG-132, blocking the proteolytic activity of the 26S proteasome complex, did not affect total HLA-E protein levels in ovarian cancer cells, while effectively downregulating surface HLA-E expression." (PMID 38007483, 2023). "MSLN was positively correlated with immunosuppressive genes in ovarian cancer, such as LGALS9, CD276, TMIGD2, CD200, TNFRSF14, and human leukocyte antigen (HLA)-related families including HLA-DRA, HLA-DRB1, HLA-DPA1, HLA-DMA, HLA-E, etc.." (PMID 35692779, 2022). "HLA-E protein in ovarian cancer cells could not be upregulated by IFN-γ in the presence of Ruxolitinib." (PMID 38007483, 2023). "Besides, MHC molecules, including HLA-B (cor = 0.365, p = 5.69e-11), HLA-DMA (cor = 0.413, p = 7.02e-14), HLA-DPA1 (cor = 0.475, p = 2.03e-18), HLA-DQA1 (cor = 0.467, p = 8.07e-18), and HLA-E (cor = 0.447, p = 2.6e-16), were significantly correlated with the expression of SUCNR1 in ovarian cancer." (PMID 33062639, 2020). "Targeting CD94/NKG2A rather than HLA-E molecule with antagonist molecules could be key to unlock the CD94/NKG2A-mediated inhibition and to preserve the CD94/NKG2C positive signaling in cytolytic lymphocytes (CD8 T cells, NK cells, and NKT cells) infiltrating ovarian cancers." (PMID 35267497, 2022).
glioma (14 papers, 2011 to 2024). A benign or malignant brain and spinal cord tumor that arises from glial cells (astrocytes, oligodendrocytes, ependymal cells). "IDH1 mutation has been identified to be one of most important molecular pathological alterations in glioma, but HLA-E showed little association with it." (PMID 32066399, 2020). "The expression of HLA-E in gliomas has also been correlated with more aggressive pathological tumor grades in gliomas." (PMID 39329751, 2024). "In conclusion, the results indicate potential therapeutic value of NKG2C+ NK cells for treatment of gliomas and of tumors expressing adequate amounts of HLA-E." (PMID 35628668, 2022). "HLA-E is overexpressed in GBM, and HLA-DR is upregulated in gliomas compared with normal brains and is associated with poor prognosis." (PMID 34660294, 2021). "Human leukocyte antigen-E (HLA-E) has been extensively investigated in various human cancers including glioma." (PMID 32066399, 2020). "Further investigation into the roles of HLA-E and other HLA molecules in glioma can help us to obtain a better understanding of the interaction between glioma and the immune system and promote the development of relevant immunotherapy." (PMID 32066399, 2020). "A total of 261 glioma patients were enrolled, subsequently, mRNA microarray analysis was conducted to identify the relationship of HLA-E with clinicopathological features and patient survival." (PMID 32066399, 2020). "A recent study using comparative proteomics analyzed 363 proteins expressed in glioma cells and confirmed that the inhibition of NK-cell cytotoxicity is mediated by the HLA-E expressed in tumor cells." (PMID 27322426, 2016). "HLA-E expression has been also reported in adult astrocytoma and GBM, being particularly prominent in pseudopalisades associated with tumor invasion, and protects glioma cells from NKG2D-mediated lysis by NK cells in vitro." (PMID 38318504, 2023). "Additionally, previous studies also explored the role HLA-E played in the occurrence and development of glioma." (PMID 32066399, 2020). "HLA-E was significantly overexpressed in high-grade gliomas compared to low-grade gliomas (LGGs)." (PMID 32066399, 2020). "Accordingly, we hypothesized that HLA-E might be also a potential biomarker for glioma patients to predict aggressive entities and poor clinical outcomes." (PMID 32066399, 2020). "Further, knockdown of HLA-E expression enables NKG2D-mediated lysis of glioma cells by NK cells." (PMID 28623356, 2017). "Furthermore, gliomas induce upregulation and expression of HLA-G and HLA-E by GAMs in a majority of glioblastomas, thus hindering anti-glioma activity." (PMID 23983766, 2013). "The results of the DEG co-expression network showed that the HLA family (HLA-A, HLA-B, HLA-C, HLA-E, HLA-DRA, HLA-DRB1, and CD74 [HLADG]) plays a vital role in the network, suggesting that tumor immunity is involved in glioma formation." (PMID 34660294, 2021). "Moreover, the interactions of CD70, HLA-E, HVEM, FALSG, and LGALS1 expressed on the glioma cell surface and their corresponding receptors have been reported to cause T cell dysfunction, thereby enabling glioma cells to evade immune-mediated killing." (PMID 37056564, 2023). "KLRC1, an inhibitory receptor for the non-classical MHC class I molecule HLA-E, has been involved in the inhibition of innate anti-glioma immune responses." (PMID 23472076, 2013). "However, the clinical significance of HLA-E expression in glioma patients has not been elucidated." (PMID 32066399, 2020).
leukemia (13 papers, 2011 to 2025). A malignant (clonal) hematologic disorder, involving hematopoietic stem cells and characterized by the presence of primitive or atypical myeloid or lymphoid cells in the bone marrow and the blood. "Moreover, we also found a correlation between HLA-E gene polymorphism and leukemia, especially for HLA-E∗01:01:01:06." (PMID 35392495, 2022). "Therefore, we suspect that rs76971248 is very likely to be related to different types of leukemia because it has lower surface expression, thereby resulting in its lower inhibitory effect on cytotoxic lymphocytes, just like some HLA-E alleles." (PMID 35392495, 2022). "However, there is already evidence that the HLA-E∗01:03 allele is an independent predictor of the early treatment needs of CLL patients, which proves the polymorphism of the HLA-E gene, as a disease marker, plays an important role in the occurrence and development of leukemia." (PMID 35392495, 2022). "With lirilumab as with ICIs, CD94-NKG2A receptors on NK cells primarily recognize HLA-E, which is expressed by leukemia cells." (PMID 31027331, 2019). "Previous studies have demonstrated that anti-NKG2A mAb can induce NKG2A+ NK cell killing activity against HLA-E-expressing leukemia cells in vitro and in vivo." (PMID 31027331, 2019). "Leukemia patients who are typed as T/T or G/T genotype with lower HLA-E molecule expression of leukemia cells may have a better therapeutic effect of NK cell infusion compared to the patients with G/G genotype." (PMID 35392495, 2022). "Higher expression and peptide binding affinity of HLA‐E*01:03 were also proposed to be the cause of a reduced probability of relapse, due to the increased efficiency of peptide presentation to CD8+ T cells inducing a stronger graft‐versus‐leukaemia (GvL) effect." (PMID 40764252, 2025). "The recognition of HLA-E by NK cells may represent a mechanism for immunosurveillance of normal biosynthesis of HLA class I molecules, a process dampened in certain virus-infected or cancer cells including leukemia." (PMID 36419901, 2022). "While the discovery of polymorphisms in the regulatory region has greatly enriched, the relationship of HLA-E SNP sites in the regulatory region and tumors has not been reported, especially for leukemia." (PMID 35392495, 2022). "The reason why there is no relevant research on the SNP sites of the HLA-E regulatory region and leukemia may be the low frequency of these SNP sites in some populations and the lack of suitable methods for screening them." (PMID 35392495, 2022). "The rationale for using a human parental cell line was based on our previous experience with heterologous CD94/NKG2C+ rat basophilic leukemia cells (RBL), which failed to respond to receptor engagement by HLA-E+ .221-AEH cells (not shown)." (PMID 29114247, 2017).
lymphoma (13 papers, 2015 to 2025). A malignant (clonal) proliferation of B- lymphocytes or T- lymphocytes which involves the lymph nodes, bone marrow and/or extranodal sites. "In agreement with our findings, a recent study identified the HLA-E*0101 variant as a protective factor for EBV+ cHL and EBV+PTLD, which further confirms that the HLA-E genotype impacts the development of EBV-associated lymphomas." (PMID 37426645, 2023). "However, recent studies have also reported a high prevalence of the HLA-E*01:03/01:03 genotype among patients with EBV-associated lymphomas, suggesting a link between this allele and impaired immune control of EBV-infected cells." (PMID 41283666, 2025). "A potential biological rationale for the genetic association with EBV-associated lymphomas described herein could be the influence of HLA-E polymorphism on CD94/NKG2A signaling in NK cells." (PMID 26261988, 2015). "Together, this data demonstrates that both HLA-E positive tumour cells and NK cells are present in the tumour microenvironment of lymphoma patients." (PMID 40977848, 2025). "Downregulation of HLA-E on lymphoma cells by selinexor therefore removes this inhibitory signal and leads to enhanced cytokine production and cytotoxicity of NK cells." (PMID 34926302, 2021). "In probing the likely mechanism, we identified that XPO1 inhibition significantly reduced the surface expression of HLA-E on lymphoma cell lines and on primary chronic lymphocytic leukemia cells." (PMID 34926302, 2021). "Our data identifies that XPO1 inhibition sensitizes lymphoma cell lines to NK cell mediated killing via downregulation of HLA-E and subsequent activation of NKG2A+ NK cells." (PMID 34926302, 2021). "Taken together these data show that selinexor downregulates HLA-E surface expression on lymphoma cell lines (SUDHL4, JeKo-1 and RAMOS) and primary CLL cells." (PMID 34926302, 2021). "The same studies identified distinct EBV latent membrane protein 1 (LMP-1)-derived peptide variants that strongly upregulate HLA-E and are associated with potent inhibition of NKG2A+ NK cells, findings predominantly observed in EBV-associated lymphoma patients." (PMID 41283666, 2025). "Thus, the HLA-E/LMP-1/NKG2A pathway and individual NKG2C+ NK cell responses are associated with the progression toward EBV+ lymphomas." (PMID 37426645, 2023). "The finding that HLA-E prevents the control of EBV-infected lymphoma cells via the stimulation of the inhibitory NKG2A receptor prompted us to test, whether the monoclonal antibody (mAB)-mediated blocking of NKG2A led to an effective control of EBV-infected tumor cells." (PMID 37426645, 2023). "In contrast, the LMP-1 GSDPHLPTL and GGDPHLPPL variants, both frequently found in patients with symptomatic or asymptomatic EBV reactivations, but not in EBV+ lymphoma patients, showed only a low capacity to upregulate HLA-E on the surface of Raji cells." (PMID 37426645, 2023). "Other strategies to inhibit the NKG2A/HLA-E axis are based on NKG2A downregulation in NK cells by dasatinib, or the reduction of HLA-E levels in tumor cells, by drugs such as bortezomib, dinaciclib or selinexor, tested in vitro on MM, AML, and lymphoma, respectively." (PMID 35990652, 2022). "We uncovered, that the interplay of three factors, a specific viral LMP-1 peptide variant of the infecting EBV-strain, the high-expressing host HLA-E*0103/0103 genotype and the absence of a potent host NKG2C+ NK cell response, is associated with a particularly high-risk for these EBV+ lymphomas." (PMID 37426645, 2023).
Autoimmunity (11 papers, 2013 to 2025). The occurrence of an immune reaction against the organism's own cells or tissues. "The pathogenic role of NKG2C T cells in CNS autoimmunity is further supported by post-mortem analyses of MS brain tissue, which show that HLA-E is upregulated on oligodendrocytes in active lesions, where it colocalizes with infiltrating NKG2C+ CD4+ T cells." (PMID 41283666, 2025). "HLA-E-mediated immune regulation thus plays a pivotal role in maintaining self-tolerance and preventing autoimmunity." (PMID 41283666, 2025). "Notably, when focusing on individual interactions of the cDCa cluster, MHC class II-related transcripts (eg, CD74, HLA-E) were predicted to interact with surface molecules such as MIF or KLRC1 with immunomodulatory capacity and known association to autoimmunity." (PMID 34783307, 2021).
cervical carcinoma (10 papers, 2011 to 2025). A carcinoma arising from either the exocervical squamous epithelium or the endocervical glandular epithelium. "In cervical cancer, we and others have described loss of classical HLA class I, and expression of HLA-E and HLA-G at the site of the primary tumor." (PMID 27895918, 2016). "Univariate and multivariate analyses were performed to determine whether HLA-E expression was associated with disease-specific and recurrence-free survival in cervical cancer patients." (PMID 22947189, 2012). "Furthermore, we investigate the associations between HLA-E expression, clinicopathological parameters, and disease-specific and recurrence-free survival of these cervical cancer patients." (PMID 22947189, 2012). "However, functional studies will be needed to further unravel the role of HLA-E expression and the underlying mechanisms in cervical cancer and in cervical AC in particular." (PMID 22947189, 2012). "High expression of HLA-E occurred in the majority of all histopathological subtypes of cervical cancer; especially in cervical AC." (PMID 22947189, 2012). "For 133 cervical cancer patients, HLA-E expression was assessed via tissue cores confined in a TMA; for 74 cervical AC patients, expression was assessed in whole tissue sections (15 AC cases overlap)." (PMID 22947189, 2012). "Staining patterns exhibiting high HLA-E protein expression were detected in the majority of cervical carcinomas." (PMID 22947189, 2012). "This study was designed to determine the differences in HLA-E expression in the three most common histopathological subtypes of cervical cancer." (PMID 22947189, 2012). "In 83% of cervical cancer samples, HLA-E expression was higher in tumour cells compared to the paired normal cervical epithelium." (PMID 22947189, 2012). "In the present study we have detected high expression of HLA-E in the majority of the three most common histopathological subtypes of cervical cancer." (PMID 22947189, 2012). "High expression of HLA-E was found in 107/192 (56%) cervical carcinomas, with significantly more overexpression in cervical AC compared to SCC and ASC (37/79 SCC, 18/38 ASC, and 52/75 AC; P = 0.010)." (PMID 22947189, 2012). "HLA-E expression was found to increase significantly with the progression from normal epithelium to virally infected lesions to cervical intraepithelial neoplasia grade 1, grade 2–3, and cervical cancer." (PMID 22947189, 2012). "By contrast, there are approximately three times more circulating CTLs in the cervical cancer TME, dampening the prognostic effect of HLA-E." (PMID 41463341, 2025). "Until now only HLA-E was studied in SCC and AC primary cervical cancer samples and high expression of HLA-E was found in 56 %, with significantly higher expression in cervical AC compared to SCC." (PMID 27895918, 2016). "This difference in HLA-E expression between the histological subtypes was remarkable and motivated investigation of the role of HLA-E in the AC and ASC subtypes of cervical cancer." (PMID 22947189, 2012). "No other correlations were found between cytotoxicity levels and HLA-E or HLA-G expression levels on cervical cancer cell lines (data not shown)." (PMID 27783105, 2017). "Classical (HLA-A and HLA-B/C)- and non-classical HLA molecules (HLA-E and HLA-G) were studied on primary tumors and paired lymph node (LN) metastases from cervical cancer patients (n = 136) by immunohistochemistry." (PMID 27895918, 2016). "Ovarian and cervical cancers have been reported to exhibit an upregulated expression of HLA-E, a ligand for the inhibitory CD94/NKG2A complex and the upregulation of HLA-E and the infiltration of cytolytic T cell populations could be neutralized by strong overexpression of the NKG2A ligand." (PMID 23378947, 2013).